CRP (C-reactive protein)
Diseases named in the same sentence as CRP in open-access papers (continued):
Sharing a sentence is not in itself a finding about the gene and the disease.
anemia (continued). "Of the nine laboratory parameters investigated that correlate with disease severity (e.g., hypergammaglobulinemia, hypoalbuminemia, C-reactive protein, etc.), all were comparably altered in both sexes except for anemia, which was more frequently detected in women." (PMID 34436194, 2021). "In addition, the pooled estimate of high CRP on the onset of anaemia was 1.40 (95% CI, 1.04 to 1.89, I2 = 0%)." (PMID 34372781, 2021). "Effect of MNP on haemoglobin, anaemia, iron biomarkers and CRP among study participants." (PMID 33571267, 2021). "Laboratory investigations revealed an elevated white blood cell count of 5450/μL (neutrophil count 4180/μL), microcytic anemia (hemoglobin level 9.8 g/dL), CRP 0.64 mg/dL [normal < 0.30 mg/dL], and persistently elevated gamma glutamyltransferase 40 U/L [normal < 30 U/L]." (PMID 32831055, 2020). "Blood tests may show anemia, eosinophilia, elevated C-reactive protein, and erythrocyte sedimentation rate." (PMID 32232639, 2020). "In addition, anaemia was more common in females, while elevated levels of CRP, creatinine and creatine kinase and decreased levels of platelets and CD4+ cells were more common in males." (PMID 33009426, 2020). "In the current study serum IL-6 level was strongly correlated with various clinical inflammatory parameters (serum CRP, hemoglobin, and albumin levels), and the prevalence of anemia, hypoalbuminemia, and CRP elevation were significantly greater in the higher IL-6 group than in the other two groups." (PMID 31951598, 2020). "Although the prevalence of anaemia is low in this population, elevated CRP in almost half indicates that inflammation may mask iron deficiency." (PMID 33101717, 2020). "In this study, failure toidentify cause of anemia (i.e., lack of ferritin and CRP results after documentedanemia) and failure to perform annual anemia assessments generally provide evidenceof a gap between guidelines and clinical practice." (PMID 33237166, 2020). "In pregnant women in the same study area, CRP was a major predictor of anemia." (PMID 33017433, 2020). "Throughout his stay, labs were pertinent for anemia, which required blood transfusions, hypergammaglobulinemia, elevated C-reactive protein (CRP), low cluster of differentiation 4 (CD4) count of 173 cells/mm3, undetectable HIV RNA, and an elevated procalcitonin." (PMID 32399323, 2020). "Furthermore, a previous study demonstrated that anemia in IBD patients was significantly associated with increased ESR, CRP, and CDAI, and that the disease activity scores showed an inverse correlation with the Hb level." (PMID 31304061, 2019). "The work-up and diagnosis of unexplained anemia in the elderly may include the measurement of inflammatory markers such as CRP and erythrocyte sedimentation rate, interleukin-6, and hepcidin levels." (PMID 30836932, 2019). "Laboratory data revealed anemia with coombs test (+), and elevated CRP." (PMID 31412876, 2019). "Our patient demonstrated both the major criteria of histopathological iMCD lymph node features and diffuse lymphadenopathy; along with the minor criteria of anemia, thrombocytopenia, hypoalbuminemia, elevated CRP, renal dysfunction, hepatosplenomegaly, ascites, and constitutional symptoms." (PMID 31453020, 2019). "• Loss of lean tissue mass, with a weight loss >5% of body weight in 12 months; Or• BMI lower than 20, plus three of the following: decreased muscle strength, fatigue, anorexia, low fat-free mass index, increase of inflammation markers such as CRP or IL-6, anemia, and low serum albumin." (PMID 31681777, 2019). "Another possible pathway could be pre-existing chronic illness resulting in low-grade inflammation raising CRP, which would lead to anemia of chronic illness and hypoalbuminemia." (PMID 31095609, 2019).
anemia (continued). "Laboratory tests showed that elevated serum ALT/AST, creatinine, and BUN levels were observed in patients with A. phagocytophilum infection, but elevated serum CRP levels, thrombocytopenia, and anemia were only observed in patients with concurrent scrub typhus and HGA." (PMID 31539395, 2019). "Blood tests showed hypochromic microcytic anaemia (haemoglobin 9.2 g/dl), mild eosinophilia (558 eosinophils/μl), hyperglycaemia (265 mg/dl), increased erythrocyte sedimentation rate (99 mm/h, normal values <13) and CRP (8.43 mg/dl, normal values <1)." (PMID 31364552, 2019). "Here we present the possibility that tocilizumab might be an effective treatment for RA with MDS, especially in those with high levels of IL-6, elevated CRP, and severe anemia." (PMID 29924032, 2018). "There is evidence that levels of hepcidin correlate with the inflammatory marker CRP but the relation between hepcidin levels and the severity of inflammatory diseases is complex, with factors such as levels of stored iron and anemia playing a role." (PMID 29744352, 2018). "In both conditions the erythrocyte sedimentation rate (ESR) and the C-reactive protein (CRP) are elevated, and anemia and thrombocytosis may occur." (PMID 29680850, 2018). "Recently, the effect of adjusting ferritin-based diagnostic criteria for iron deficiency according to levels of CRP or AGP was examined using data from the international Biomarkers Reflecting Inflammation and Nutritional Determinants of Anemia (BRINDA) project." (PMID 29744352, 2018). "Univariate logistic regression analysis yielded ten univariate mortality predictors, each with a significance of p < 0.1: tachypnea, severe coma, hypertension, coronary artery disease, cancer, bedridden, leukocytosis, bandemia, anemia, and elevated C-reactive protein levels (CRP)." (PMID 29915256, 2018). "In addition, almost all the laboratory findings were within the normal ranges including the C-reactive protein (CRP) level, with the exception of anemia (hemoglobin, 9.9 g/dL) and malnutrition (albumin, 3.0 g/dL)." (PMID 30069647, 2018). "Tocilizumab might be an effective treatment for RA with MDS, especially in those with high levels of IL-6, elevated C-reactive protein, and severe anemia." (PMID 29924032, 2018). "CRP has been associated to paraneoplastic symptoms and cachexia, leading to an understanding of a condition with chronic elevated IL-6 in cancer which leads to anemia, elevated CRP levels and a change in the gut microbiota that possibly increases the gut permeability further worsening the cachexia." (PMID 30038723, 2018). "IL-6 may be a driver of downstream systemic inflammation in HS inducing CRP, hepcidin and anaemia of chronic disease, immunoglobulins, Th17 differentiation, as well as contributing to other features seen in HS such as depression." (PMID 30265680, 2018). "Factors significantly associated with hepcidin levels were serum ferritin and CRP, although neither of these were independently associated with anemia." (PMID 30056060, 2018). "In addition to body weight loss and composition, blood measurements include only albumin, anemia, CRP, and absolute lymphocyte number; together with a questionnaire containing two questions related with PHP, two related with ANO and 11 related with QoL." (PMID 28261113, 2017). "Therefore, we excluded participants with anemia and iron overload, used inflammation-adjusted ferritin concentration as ferritin level and adjusted for CRP levels in the multivariable logistic regression analyses in our study." (PMID 29272309, 2017). "Incident MPA patients are predominantly males (1.8:1.0) with an average age of onset between 50 and 60 years and with predominant increase of non-specific markers of inflammation (erythrocyte sedimentation rate and C reactive protein) and normochromic, normocytic anemia." (PMID 28243232, 2017).
anemia (continued). "It is important, however, to obtain a complete blood count to ensure the absence of an iron deficiency anemia, and a CRP can be requested to lower the suspicion for inflammatory bowel disease." (PMID 29072609, 2017). "Likewise, the presence of anaemia independently predicted reduced exercise capacity after adjusting for age, gender, creatinine, CRP, LVEF, the presence of ID, and natriuretic peptide levels (OR 1.939, 95% CI 1.356–2.773, p = 0.0003)." (PMID 28229219, 2017). "In both conditions sedimentation rate and C-reactive protein are elevated, and anemia and thrombocytosis may occur." (PMID 27824543, 2016). "The diagnosis of PMR and GCA is made primarily on clinical grounds and is bolstered by laboratory evidence of an acute-phase reaction, most commonly elevated levels of erythrocyte sedimentation rate (ESR) and C-reactive protein (CRP), as well as anemia of inflammation and thrombocytosis." (PMID 27824543, 2016). "While both patient groups had rather mild anemia and elevated CRP, the patients with unexplained anemias more often had suffered a fall, even though they had fewer diagnoses, were using fewer drugs and had a lower pro-BnP, indicative of less cardiovascular disease." (PMID 27221100, 2016). "A laboratory examination found anemia (hemoglobin: 9.1 g/dl), hypoalubuminemia (2.1 g/dl), hypergammaglobulinemia (IgG: 6627 mg/dl, IgA: 798 mg/dl, IgM: 765 mg/dl) and an elevation of serum levels of CRP (9.8 mg/dl) and the serum IL-6 level (131 pg/ml)." (PMID 27146847, 2016). "Thus, in contrast to anemia and CRP level, the AHI offers a direct measure of the blood supply deficiency in patients with PAD." (PMID 27760183, 2016). "In addition, as a marker of anemia of chronic disease, CRP and hepcidin which are induced and elevated in inflammatory condition, were assessed." (PMID 26517509, 2015). "In spite of the increased EPO blood levels, anemia persisted and was linked to low serum iron and transferrin levels, while serum interleukin (IL)-6 and high sensitivity C-reactive protein (hs-CRP) levels showed the absence of systemic inflammation." (PMID 25867633, 2015). "Other variables that could have an effect on anaemia control, such as CRP levels and the frequency and duration of dialysis, were similar between periods." (PMID 26322790, 2015). "Laboratory findings included elevated CA-125, anemia, leucocytosis and high C-reactive protein." (PMID 26854159, 2015). "However, despite overall higher concentrations of CRP and hepcidin in the anemic group, only 15% infants at 3 months fulfilled the strict criteria for anemia of inflammation." (PMID 26252205, 2015). "HIV-MCD presents with various clinical symptoms, including fever, swelling of the spleen, liver and systemic lymph nodes and abnormalities in laboratory values, such as findings of anemia, thrombocytopenia or hypergamma-globulinemia, as well as a low albumin, or high C-reactive protein (CRP) level." (PMID 24438824, 2014). "Laboratory investigations demonstrated anaemia (Hb: 7.9 g/dL), raised CRP at 133 mg/l and leucocytosis (WCC 14.3 × 103/μl).Gastro-duodenoscopy revealed mild chronic gastritis and reactive gastropathy whilst colonoscopy ruled out the possibility of inflammatory bowel disease." (PMID 27231558, 2014). "Another limitation was due to the fact that anaemia was measured based on hemoglobin concentration only, inclusion of other measures such as C-reactive protein (CRP) and plasma ferriton (PF) concentration could lead to better diagnosis results." (PMID 25423084, 2014). "This fact is to be brought to the attention to clinicians who might underestimate ALA size when expecting higher White Blood Cells count, C Reactive Protein level and more severe anemia for bigger abscess." (PMID 23951372, 2013).
anemia (continued). "When testing small volume (2.0 ml) urine samples, the diagnostic sensitivity was not only greater among those with lower CD4 counts as previously reported, but was also higher among those with higher CRP concentrations, severe anemia and in those who later died." (PMID 24168211, 2013). "Of those, only 2 (10.5%) patients were diagnosed not having an iron-deficiency anemia due to the criteria not having microcytosis and normal CRP." (PMID 22899905, 2012). "Among infants and toddlers, almost one in five cases of anemia was attributable to ID; purchasing power, serum concentrations of vitamin B12 and retinol, and elevated CRP concentrations as a measure of recent infection were additional factors shown to affect Hb concentrations." (PMID 22574149, 2012). "Other nonspecific diagnostic abnormalities include anemia, hypoalbuminemia, polyclonal gammopathy, elevated erythrocyte sedimentation rate or C-reactive protein concentration, and proteinuria, which is not found in the localized form." (PMID 23227386, 2012). "Systemic features of inflammation and anemia are frequently present, and blood cultures are positive in 50-85% of cases On admission our patient had elevated C reactive protein, leukocytosis and positive blood cultures; anemia wasn't present (hemoglobin - 14.5 g/dl)." (PMID 20072682, 2009). "Laboratory investigations revealed anemia (hemoglobin 9.6 g/dL), leukocytosis (10,600/mm3), elevated creatinine (1.64 mg/dL), hyperbilirubinemia (2.23 mg/dL), and markedly elevated levels of procalcitonin and C-reactive protein/CRP (2.94 ng/mL and 203.9 mg/L, respectively)." (PMID 40864107, 2025). "The lack of significant correlation between MPV and DAS28-ESR warrants further investigation but could potentially relate to differences in the biological processes reflected by CRP (acute-phase reactant) versus ESR (influenced by multiple factors including anemia and immunoglobulin levels)." (PMID 40797437, 2025). "Approximately 15%–30% of IMT patients may experience systemic symptoms including unexplained fever, weight loss, anemia, thrombocytosis, polyclonal hyperglobulinemia, and elevated erythrocyte sedimentation rate (ESR), procalcitonin (PCT), and c-reactive protein (CRP) levels." (PMID 40260197, 2025). "Additionally, the co-occurrence of anemia with elevated AGP or CRP, supports the “anemia of inflammation” hypothesis where inflammation disrupts iron metabolism and contributes to anemia." (PMID 40526587, 2025). "Additionally, higher CRP levels among overweight and obese women in the cohort support existing evidence linking chronic inflammation from adiposity to impaired iron metabolism and anemia of chronic disease." (PMID 41458907, 2025). "The laboratory examination revealed the presence of anemia (hemoglobin: 62 g/L (NR, 99–196 g/L)), accompanied by elevated levels of leukocytes (32 × 109/L (NR, 5–12 × 109/L)), platelets (893 × 109/L (NR, 100–300 × 109/L)), and C-reactive protein (34 mg/L (NR, <8 mg/L))." (PMID 40635052, 2025). "Anemia influences certain inflammatory mediators, such as CRP, which, when elevated, are linked to higher mortality in hip fracture patients, indicating that anemia-related inflammation may lead to negative outcomes." (PMID 40337739, 2025). "In addition, 35.0% of anemic children had elevated C-reactive protein (CRP), suggesting that anemia of inflammation may contribute in about one-third of cases." (PMID 40723025, 2025). "Therefore, whether CRP and the inflammatory state represented by CRP will further aggravate the decrease in serum iron levels, thus contributing to anemia, warrants further study." (PMID 38562035, 2024). "However, in our final model, which included adjustments for ESA use and C-reactive protein, anemia remained associated with total FGF23 but not intact FGF23, suggesting that neither of these factors markedly confounded our observations." (PMID 37752381, 2024).
anemia (continued). "We propose that in the presence of multiple infections associated with Th2 cytokine profiles, CRP may not be the best indicator of inflammation when studying anemia, as shown in the lack of association of CRP with anemia or Hb." (PMID 38892681, 2024). "Anemia of inflammation has been described as usually mild, presenting with erythrocytes of normal size (normocytic) and Hb content (normochromic), decreased serum iron but replete iron stores (ferritin > 100 mg/L), elevation of inflammatory markers (CRP, IL-6), and elevated hepcidin." (PMID 38892681, 2024). "However, the association between large fish and anaemia was no longer statistically significant after adjusting for CRP at endline." (PMID 38217291, 2024). "Patients returning to dialysis may exhibit worse anemia and hypoalbuminemia, have worse C-reactive protein (CRP) levels, and have a poorer erythrocyte sedimentation rate (ESR) than non-transplant dialysis patients with an associated increase in cardiovascular risk, morbidity, and mortality." (PMID 37675360, 2023). "In addition, CRP levels can predict iron reactivity in patients with anemia." (PMID 37685462, 2023). "Since the patient had no history of special diseases or medications, her body temperature and CRP were normal when she was admitted, and the patient’s severe anemia could explain her mild tachycardia, suggesting that there was no inflammation before the operation." (PMID 38050245, 2023). "Elevated NLR but not CRP is associated with an increased risk of anemia in female subjects." (PMID 37763711, 2023). "Moreover, measurement and evaluation of serum CRP and serum hemoglobin levels could also help to uncover undiagnosed or unreported inflammatory diseases or subclinical anemia to exclude such individuals from our study." (PMID 36980461, 2023). "Patients without anaemia undergoing elective cardiac surgery will be allocated to an iron-deficient and an iron-replete group based on standard pre-operative blood tests (ferritin, transferrin saturation and C-reactive protein)." (PMID 35130975, 2022). "Additionally, CKD severity is positively correlated with the severity of anemia and CRP levels." (PMID 35528157, 2022). "Because the study only included 24 patients with hip TB, it could not investigate other comorbidities associated with anemia and CRP elevation, such as pulmonary TB, systemic disease, gout, and rheumatoid arthritis." (PMID 36578841, 2022). "Maternal anemia was the strongest predictor for prematurity in association with SARS-CoV-2 infection (β = 3.65, CI = 1.46–5.39, p-value < 0.001), followed by elevated CRP (β = 2.11, CI = 1.20–3.06, p-value < 0.001), and respectively IL-6 (β = 1.92, CI = 1.20–2.47, p-value = 0.001." (PMID 36579593, 2022). "Laboratory evaluation showed normocytic normochromic anemia (10 g/dl) with increased ferritin and low serum iron, transferrin and transferrin saturation, typical of anemia of inflammation, leukocytosis (13,000/mL, neutrophiles 73%) and high-sensitivity C-reactive protein (158 mg/dl)." (PMID 36175842, 2022). "Moreover, a higher incidence of ID has been observed in anemic patients (even though it is an independent condition of anemia), and also in women, diabetics, more advanced functional class, greater burden of comorbidities, and higher levels of C-reactive protein and NT-proBNP." (PMID 36362983, 2022). "Although it is impossible to infer causality in this study, the association between high CRP levels with low hemoglobin and CRP and VitA levels suggests that inflammation secondary to acute phase response, which is present in individuals with VL52, can partially explain anemia and VitA deficiency." (PMID 34495261, 2021). "Few studies that examined anemia have addressed potential predictors or factors associated with anemia such as age, sex, family history of IBD, clinical disease activity, and inflammatory biomarkers, such as high C-reactive protein (CRP), erythrocyte sedimentation rate (ESR), and albumin." (PMID 33467587, 2021).